ATG5 (autophagy related 5)
Diseases named in the same sentence as ATG5 in open-access papers (continued):
Sharing a sentence is not in itself a finding about the gene and the disease.
scrapie (4 papers, 2018 to 2021). A fatal disease of the nervous system in sheep and goats, characterized by pruritus, debility, and locomotor incoordination. "Downregulation of these positive autophagy gene regulators (Becn1, Fbxw7, Gas5 and Atg5) has been described in the CNS of scrapie-infected mice (both wild-type or transgenic) and naturally scrapie infected sheep." (PMID 34283400, 2021). "In contrast, ATG5 protein accumulates in medulla oblongata and positively correlates with prion deposition and scrapie-related lesions." (PMID 30760781, 2019). "In contrast to the transcript levels, ATG5 protein was significantly increased in the Mo of scrapie infected animals (P = 0.029), and specifically in the NTN (P = 0.028)." (PMID 30760781, 2019). "Moreover, in contrast to its reduced transcript levels, ATG5 protein increased in one of the most affected areas of the CNS of scrapie-infected animals, the nucleus of the trigeminal nerve spinal tract of medulla oblongata." (PMID 30760781, 2019). "It is plausible that increased ATG5 immunostaining observed here in highly affected areas in scrapie brains could reflect the induction and subsequent accumulation of non-functional autophagosomes in neurites, which may contribute to the development of prion disease." (PMID 30760781, 2019). "Gene expression of autophagy markers ATG5 and ATG9 was downregulated in some areas of scrapie brains." (PMID 30760781, 2019). "We carried out a first gene expression analysis of ATG5, BECN1, ATG9 and LC3-B in naturally scrapie-infected sheep brains." (PMID 30760781, 2019). "However, a significant downregulation was observed for ATG5 (P < 0.05) in T and ATG9 (P < 0.01) in Cbl of scrapie-infected animals." (PMID 30760781, 2019). "However, the strong negative correlation observed between ATG5 and prion deposition in thalamus in the total set of individuals (ρ = −0.739, P < 0.01) was maintained in scrapie tissues (ρ = −0.833, P < 0.05)." (PMID 30760781, 2019). "Here, transcript expression levels of genes ATG5 and ATG9 decreased significantly in thalamus and cerebellum, respectively, of scrapie-infected sheep, and BECN1 expression displayed a negative correlation with prion deposition in scrapie thalamus." (PMID 30760781, 2019). "As opposed to ATG5, LC3-B levels were not modified in the neuronal nuclei of the Mo of scrapie-infected animals and LC3-B protein levels did not correlate with those of its transcript (data not shown)." (PMID 30760781, 2019).
aortic aneurysm (3 papers, 2020 to 2021). A ruptured aneurysm located in the wall of the proximal portion of the descending aorta proceeding from the arch of the aorta. "In this model, blocking autophagy in VSMCs through the deletion of Atg5 resulted in increased severity and incidence of aortic aneurysm dissection, decreased autophagosome formation, and increased VSMC apoptosis." (PMID 34403365, 2021). "Moreover, p62, IL-6, Rab7, and Atg5/IRE1α pathways of autophagy may play a role in aortic aneurysm and aortic dissection, and can be considered a novel super-selective therapeutic target." (PMID 34754985, 2021).
astrocytoma (3 papers, 2020 to 2025). "Meanwhile, ATG5 (autophagy-related gene 5) is a proapoptotic molecule that has been demonstrated to be linked to the immune system and increased in the presence of hypoxia in GB and astrocytoma." (PMID 41294712, 2025).
breast tumors (3 papers, 2021 to 2024). "In human breast tumor tissues, the expression levels of Beclin-1 and ATG5 were significantly higher in stage I breast tumor tissues." (PMID 33806593, 2021). "Moreover, the knockdown of TRPV2 in xenograft breast tumors led to the suppression of autophagy, as evidenced by evaluated SQSTM1 levels and decreased expression of ATG5 and LC3." (PMID 39334351, 2024).
Cerebral ischemia (3 papers, 2017 to 2022). Restriction of arterial blood supply to the brain associated with insufficient oxygenation to support the metabolic requirements of the tissue. "SNHG14 promotes the expression of Atg5 and Beclin 1 by sponging miR-30b-5p, thereby activating autophagy and aggravating cerebral ischemia-reperfusion injury." (PMID 36275741, 2022). "The levels of autophagy-related proteins, including Beclin-1, Atg3, Atg5, and LC3 in the hippocampus were effectively maintained and elevated at 28 days after cerebral ischemia/reperfusion in the young gerbils compared with those in the old gerbils." (PMID 35220404, 2022). "Both cerebral ischemia and ischemia-reperfusion can activate autophagy by inducing high expression of certain genes, including Becn1, LC3-II, and Atg5." (PMID 29088811, 2017).
cholestasis (3 papers, 2022 to 2024). Impairment of the bile flow caused by obstruction within the liver, or outside the liver in the bile duct system. "Mice deficient in Atg5 or Atg7 exhibit increased accumulation of p62, which correlates with more severe intrahepatic cholestasis, suggesting that defective autophagy exacerbates cholestatic liver injury." (PMID 39061903, 2024). "In addition, hepatic deletion of autophagy-associated genes Atg5 or Atg7 lead to autophagy-deficient in mice, which promotes intracellular cholestasis with the increased level of bile acids." (PMID 35930537, 2022). "First, to verify and further define cholestasis-dependent changes in autophagy proteins in our PSC samples, expression of p62, Beclin1, LC3a/b, ATG5/12, ATG7, LAMP1 and LAMP2 was evaluated by Western blotting using lysates prepared from PSC liver tissue." (PMID 36378690, 2022).
cognitive decline (3 papers, 2019 to 2024). "However, there is a discrepancy with a recent report that Itgam/CD11b‐Cre‐mediated microglial Atg5 depletion caused early PD‐like neurodegeneration, which displayed motor coordination defects at 3 months old and cognitive decline at 8‐month‐old mice." (PMID 34811872, 2021). "The measurement of serum levels of ATG5 and Parkin may represent an easily accessible diagnostic tool for the early monitoring of patients with cognitive decline." (PMID 31882960, 2019). "Furthermore, the measurement of serum levels of ATG5 and Parkin, as biomarkers of autophagy and mitophagy, respectively, may represent an easily accessible diagnostic tool for the early monitoring of patients with cognitive decline." (PMID 31882960, 2019). "In this study, for the first time, the presence of specific autophagic (ATG5 protein) and mitophagic (Parkin protein) markers were investigated in the serum of both patients affected by different types of cognitive decline and in sex-matched healthy individuals." (PMID 31882960, 2019).
dengue virus infection (3 papers, 2014 to 2024). "Other canonical autophagy factors, specifically ULK1, Beclin-1, and ATG5 are dispensable during dengue virus infection." (PMID 33173007, 2020). "Notably, the knock-down of either ATG5 or ATG16L1, essential autophagy molecules for autophagosome formation, led to a reduction in dengue virus infection of DCs." (PMID 38863700, 2024). "In conclusion, several mechanisms have been previously proposed for ADE in dengue disease pathogenesis including promoting viral entry into FcR-bearing cells, the induction of IL-10 to inhibit the IFN-mediated anti-viral pathway, and the activation of DAK and Atg5-Atg12 to inhibit IFN production." (PMID 25329914, 2014).
diabetic nephropathy (3 papers, 2024 to 2025). "Studies have shown that endothelial cell-specific knockout of atg5 could result in capillary rarefaction and accelerated diabetic nephropathy." (PMID 39316662, 2024). "In contrast, deletion of the Atg5 autophagy component in podocytes resulted in accelerated podocyte injury and albuminuria in STZ diabetic nephropathy." (PMID 39480824, 2024).
dilated cardiomyopathy (3 papers, 2021 to 2023). Cardiomyopathy which is characterized by dilation and contractile dysfunction of the left and right ventricles. "Animals bearing a cardiomyocyte-specific deletion of autophagy-related 5 (Atg5), a protein engaged in the extension of the phagophore membrane in autophagic vesicles, suffer from dilated cardiomyopathy in adulthood." (PMID 37221467, 2023).
encephalitis (3 papers, 2017 to 2023). An acute inflammatory process affecting the brain parenchyma. "Notably, several key autophagic factors, such as BECN1, ATG5, ATG7, and LC3-II, were found to be elevated in the postmortem brains of HIV-1 encephalitis patients compared to HIV-1 patients without encephalitis." (PMID 37445802, 2023). "In post-mortem brains from HIV-1 patients with encephalitis, levels of autophagy proteins such as Beclin 1, ATG5, ATG7, and LC3-II were significantly increased, as compared to the brains from HIV-1 positive patients without HIV-1 encephalitis or uninfected controls." (PMID 33669846, 2021).
endothelial dysfunction (3 papers, 2020 to 2024). In vascular diseases, endothelial dysfunction is a systemic pathological state of the endothelium (the inner lining of blood vessels) and can be broadly defined as an imbalance between vasodilating and vasoconstricting substances produced by (or acting on) the endothelium. "Oxidative stress (Nox2 activity and hydrogen peroxide, H2O2), platelet activation (PA) by sP-selectin and CD40L, endothelial dysfunction (nitric oxide, NO), and autophagy parameters (P62 and ATG5 levels) were assessed." (PMID 35453383, 2022).
epilepsy (3 papers, 2017 to 2023). A brain disorder characterized by episodes of abnormally increased neuronal discharge resulting in transient episodes of sensory or motor neurological dysfunction, or psychic dysfunction. "A clinical study observed that ATG5 gene polymorphisms Chinese population are linked with epilepsy." (PMID 37880579, 2023). "However, previous studies revealed that deletion of both Atg5 and Atg7 resulted in neurodegeneration without evidence of epilepsy." (PMID 37880579, 2023).
influenza (3 papers, 2018 to 2022). An acute viral infection of the respiratory tract, occurring in isolated cases, in epidemics, or in pandemics; it is caused by serologically different strains of viruses (influenzaviruses) designated A, B, and C, has a 3-day incubation period, and usually lasts for 3 to 10 days. "The increased CD8+ T cell expansion in mice with Atg5 or Atg7 deficiency in dendritic cells and some macrophage populations also correlates with improved control of viral titers and pathology in the influenza infected mice." (PMID 30542350, 2018). "Deletion of autophagy genes including Epg5, Atg14, FIP200, Atg5 and Atg7 led to influenza resistance." (PMID 36042265, 2022). "However, the induction of autophagy after influenza infection was demonstrated by detection of LC3β-II, Atg5, and p62." (PMID 31000695, 2019).
iron deficiency (3 papers, 2019 to 2025). "We assessed whether the core autophagy proteins Atg5, Atg8, Atg11 and Atg13 are involved in mitochondrial degradation upon iron deficiency." (PMID 40716740, 2025). "Moreover, we found that when compared with the wild-type plants, the atg5-1 and atg7-2 mutants showed hypersensitive phenotypes to iron-deficiency, which were reminiscent of the phenotype of FREE1 overexpression plants." (PMID 34445480, 2021). "As a consequence, the autophagy deficient mutants, atg5-1 and atg7-2, accumulate more endogenous FREE1 protein and display hypersensitivity to iron deficiency." (PMID 34445480, 2021).
ischemic stroke (3 papers, 2023 to 2025). A stroke disorder caused by obstruction of blood flow to the brain, due to thrombotic (local blood clot formation) or embolic (due to a blood clot or other material traveling from another site) event. "Preliminary clinical observations—such as elevated circulating ATG5 levels in ischemic stroke patients, which correlate with worse functional outcomes—suggest indirect translational relevance but fall short of confirming functional autophagic activity within human microglia." (PMID 41007413, 2025). "Furthermore, knockdown of ATG5 attenuates ischemia-reperfusion injury (IRI) in an experimental ischemic stroke mouse model." (PMID 38511768, 2024). "SNHG15/miR‐153‐3p/ATG5 axis was possible pathway and target in treatment of ischaemic stroke." (PMID 37845831, 2023). "First, we could not find any evidence of SNHG15/miR‐153‐3p/ATG5 gene or protein production in those who had had an ischaemic stroke." (PMID 37845831, 2023).
lymphopenia (3 papers, 2013 to 2017). Reduction in the number of lymphocytes. "The lymphopenia upon specific deletion of Atg3, Atg5, Atg7, Atg16l1, or Vps34 in T cells has been demonstrated to be associated with increased percentages of activation/memory-like T cells within both the CD4+ and CD8+ compartments." (PMID 28572806, 2017). "A hematopoietic chimeric mouse generated with Atg5−/− fetal liver results in T lymphopenia due to enhanced CD8+ T cell apoptosis and an inability to undergo TCR-induced proliferation, suggesting a crucial role of autophagy in T cell survival and function." (PMID 22669258, 2013). "In line with Atg5−/− chimeras, these mice had significantly reduced lymphoid progenitor compartments in the bone marrow (BM) and lymphopenia." (PMID 22669258, 2013). "Similarly, data from a mouse model in which another essential autophagy gene, Atg5, was deleted under the hematopoietic stem cell-specific promoter Vav, showed T cell lymphopenia and the expanded virtual memory T cell compartment (CD8+CD44+) suggesting this phenotype is not Atg7 specific." (PMID 25385531, 2014). "Enhanced T cell activation/memory in the absence of Atg3, Atg5, Atg7, Atg16l1, or Vps34 can be partially attributed to peripheral T cell lymphopenia." (PMID 28572806, 2017).
multiple sclerosis (3 papers, 2013 to 2025). A progressive autoimmune disorder affecting the central nervous system resulting in demyelination. "Enhanced expression of Atg5 was also reported in blood of mice with experimental autoimmune encephalomyelitis (EAE), a mouse model of multiple sclerosis (MS), and in T cells isolated from blood or brain tissues from patients with active relapse of MS." (PMID 23596443, 2013). "Interestingly, expression of Atg5 has been shown to correlate with severity of experimental autoimmune encephalitis (EAE), a mouse model of multiple sclerosis (MS), and to be increased in T cells of MS patients during relapses, which can worsen by prolonged autoreactive T cell survival." (PMID 23596443, 2013).
nasopharyngeal carcinoma (3 papers, 2020 to 2025). A carcinoma arising from the nasopharyngeal epithelium. "Autophagy initiation, particularly the ATG5 protein, was required for EBV lytic reactivation in nasopharyngeal carcinoma." (PMID 40630202, 2025).
osteoarthritis (3 papers, 2016 to 2020). A noninflammatory degenerative joint disease occurring chiefly in older persons, characterized by degeneration of the articular cartilage, hypertrophy of bone at the margins and changes in the synovial membrane. "We thus decided to genetically ablate the autophagy-indispensable Atg5 gene specifically in chondrocytes and analyse the development of osteoarthritis upon aging and in a post-traumatic model." (PMID 26438374, 2016). "Besides, some studies have found that in the early stage of OA, the expression of LC3 and atg5 in osteoarthritis chondrocytes were increased, suggesting that autophagy was enhanced." (PMID 32134473, 2020).
periodontitis (3 papers, 2021 to 2023). An acute or chronic inflammatory process that affects the tissues that surround and support the teeth. "For example, peripheral blood mononuclear cells (PBMCs) from patients with periodontitis showed significantly downregulated levels of the autophagy-related proteins ATG5-12 conjugate, ATG16L1, and ATG7." (PMID 36782172, 2023). "Our previous clinical study of periodontitis patients demonstrated decreased expression levels of the autophagy-related proteins ATG5-12 conjugates, ATG16L1 and ATG7, at the protein and mRNA levels." (PMID 37764988, 2023). "Interestingly, Vit D supplementation rescued autophagy in periodontitis patients, and increased the expression of Beclin1, ATG5-12 conjugate, ATG16L1 and ATG7." (PMID 37764988, 2023). "A study showed that vitamin D supplementation enhanced autophagy by upregulating the expression of these proteins in PBMCs and upregulating the expression of ATG5 and ATG16L1 in gingival tissue from patients with periodontitis." (PMID 36782172, 2023).
psoriasis (3 papers, 2020 to 2024). An autoimmune condition characterized by red, well-delineated plaques with silvery scales that are usually on the extensor surfaces and scalp. "To investigate the influence of ATG5 and paeonol intervention on psoriasis, we established an in vitro psoriatic model using IL-22/TNF-α stimuli and treated it with paeonol." (PMID 34113484, 2021). "Our study demonstrated that a cluster of psoriasis- and immunity-related genes, including the ATG5 gene, were upregulated in psoriatic lesions." (PMID 34113484, 2021). "The autophagy-related 5 (ATG5) gene was the only gene that overlapped between the DEGs and genes related to paeonol and psoriasis." (PMID 34113484, 2021). "Our study identified that the ATG5 gene had crucial roles in the pathogenesis and might be a therapeutic target in psoriasis." (PMID 34113484, 2021). "In conclusion, we confirmed that ATG5-dependent autophagy was of great value in psoriasis." (PMID 34113484, 2021). "We found that the ATG5 gene had a distinctive role in psoriasis." (PMID 34113484, 2021). "The ATG5 gene might be a therapeutic target for the management of in vitro psoriasis." (PMID 34113484, 2021). "The inhibition of ATG5 might be a targeting management strategy for in vitro psoriasis." (PMID 34113484, 2021). "We transfected si-ATG5 and pc-ATG5 into HaCaT cells and detected the expression of IL-6 and IL-1β to investigate whether the ATG5 gene could be used as a therapeutic target for the management of psoriasis." (PMID 34113484, 2021). "Moreover, the keratinocyte-specific ablation of ATG5 ameliorated imiquimod-induced skin lesions in mice accompanied by a reduction in the number of IL-17A producing cells, highlighting the role of this target in psoriasis." (PMID 32630692, 2020). "Meanwhile, the results of cellular experiments illustrated that the autophagy-related 5 (ATG5) depends on the effect of paeonol on HaCaT, certifying that the ATG5 gene may be an important target for the in vitro treatment of psoriasis." (PMID 39588155, 2024).
pulmonary arterial hypertension (3 papers, 2019 to 2025). Pulmonary arterial hypertension (PAH) is a group of diseases characterized by mean pulmonary artery pressure >20 mmHg and elevated pulmonary arterial resistance leading to right heart failure. "Meanwhile, Glucagon-like peptide 1 receptor agonists attenuate autophagy via Drp1/NOX- and Atg-5/Atg-7/Beclin-1/LC3β pathways to improve pulmonary hypertension." (PMID 37491292, 2023).
relapsing-remitting MS (3 papers, 2017 to 2021). "The ATG5 mRNA level is elevated in patients with active relapsing-remitting MS (RRMS) compared with those in quiescent RRMS." (PMID 30386331, 2018). "Expression of the essential autophagy-related protein 5 (Atg5), which supports T lymphocyte survival and proliferation, is increased in T cells isolated from blood or brain tissues from patients with relapsing-remitting MS." (PMID 28289410, 2017). "Furthermore, peripheral T cell-derived RNA analyses suggested a significant increase in Atg5 expression in patients with active relapsing-remitting MS as compared to healthy controls." (PMID 28289410, 2017). "Transcriptional analysis of peripheral T cells from patients with active relapsing-remitting MS (RRMS) and postmortem brain tissue from patients with secondary progressive MS revealed significantly elevated ATG5 expression compared to non-disease controls." (PMID 34531871, 2021).